STAT3 (signal transducer and activator of transcription 3)
Diseases named in the same sentence as STAT3 in open-access papers (continued):
Sharing a sentence is not in itself a finding about the gene and the disease.
Ureteral obstruction (17 papers, 2012 to 2025). Obstruction of the flow of urine through the ureter. "An existing report unveiled that the deletion of AKT1 accelerated kidney fibrosis through the activation of TGF-β1/STAT3 signaling in a mouse model of unilateral ureteral obstruction (UUO)." (PMID 36866869, 2023). "We studied the role of JAK2/STAT3 in a model of congenital obstructive nephropathy using unilateral ureteral obstruction (UUO) in neonatal mice at the second day of life." (PMID 31846485, 2019). "STAT3 expression rapidly increased after ureteral obstruction and localized to tubular and interstitial cells." (PMID 31846485, 2019). "al. in a unilateral ureteral obstruction (UUO) model suggest that STAT3 activation contributes to MMP-9 up-regulation and tubulointerstitial fibrosis during kidney obstruction." (PMID 30081609, 2018). "It has been reported that STAT3 plays an important role in mediating the activation of renal interstitial fibrosis in the kidney after ureteral obstruction." (PMID 29137389, 2017). "In addition, S3I‐201, an inhibitor of STAT3 phosphorylation, has been shown to have antifibrotic effects in a unilateral ureteral obstruction (UUO) model by repressing STAT3 phosphorylation." (PMID 33112058, 2020). "The expression levels of p-STAT3 increased after ureteral obstruction." (PMID 31846485, 2019). "In addition, inhibition of STAT3 with S3I–201 has been evaluated in a preclinical animal mouse model of renal interstitial fibrosis induced by unilateral ureteral obstruction." (PMID 30081609, 2018). "Kidney fibrosis was induced by unilateral ureteral obstruction (UUO), which was accompanied by upregulation of STAT3 target genes." (PMID 33112058, 2020). "In support of this hypothesis, we have recently demonstrated that the inhibition of STAT3 by S3I-201 suppressed the expression of TNF-alpha, IL-1beta, and ICAM-1 without affecting that of MCP-1 in the mouse kidney injured by ureteral obstruction." (PMID 22558380, 2012).
antibody deficiency (16 papers, 2018 to 2025). "For instance, mutations in TNFRSF13B, NFKB1, NFKB2, CTLA4 and STAT3 are indications for the early molecular diagnosis of patients with predominantly antibody deficiency such as predominantly antibody deficiencies." (PMID 37033178, 2023). "Some patients with well-characterized PIDs such as X-linked lymphoproliferative (XLP) disorder or STAT3 mutations can present rarely with predominant hypogammaglobulinemia." (PMID 31824486, 2019). "On the other hand, primary antibody deficiencies belong to the phenotypic spectrum of STAT3-GOF." (PMID 39247195, 2024). "This newly identified B-cell intrinsic impairment of STAT3 function could underlie the progressive development of hypogammaglobulinemia." (PMID 31068927, 2019). "Consequently, STAT3-GOF exemplifies an IEI blurring the dichotomous classification of hypogammaglobulinemia into primary and secondary." (PMID 39247195, 2024). "A number of previous studies have outlined the clinical phenotypes of large patient groups with antibody deficiency who have mutations in selected genes, including the TACI gene, CTLA4, NFKB1, NFKB2, STAT3, PI3KCD, or LRBA." (PMID 38274105, 2023). "Patients with STAT3 GOF mutations have prominent early-onset multiorgan autoimmune and lymphoproliferative features, though more than half of the subjects (18 of 28) also have hypogammaglobulinemia in a recent systematic review." (PMID 32117289, 2020). "We distinguish PIDs such as XLP and STAT3 mutations, which do not typically present with antibody deficiency from disorders such as NFKB1 mutations which, most often present with hypogammaglobulinemia, that are more appropriately termed CVID-like disorders." (PMID 31824486, 2019). "Four out of seven patients with STAT3-GOF had been diagnosed with a PID, which could be classified as common variable immunodeficiency (CVID) (three out of seven patients) or unclassified antibody deficiency (one out of seven patients, i.e., patient 5)." (PMID 39247195, 2024). "Most patients in the ATM (92.5%) and STAT3 (AD-LOF) (89.5%) groups had similar clinical diagnoses, however, patients with DNMT3B/ZBTB24 mutations were first diagnosed with hypogammaglobulinemia (13, 68.4%), immunoglobulin A deficiency (2, 10.5%), and agammaglobulinemia (1, 5.3%)." (PMID 36544766, 2022). "Additionally, increased STAT3 activation may impair B cell differentiation leading to hypogammaglobulinemia and heightened autoreactivity found in association with CVID or more mild forms of hypogammaglobulinemia." (PMID 31921101, 2019). "His clinical presentation was characterized by intestinal chronic inflammation and hypogammaglobulinemia, suggesting a STAT3 GOF rather than a LOF." (PMID 39873967, 2025). "Considering all seven patients with STAT3-GOF, in the case of three of them, no PID was diagnosed previously and hypogammaglobulinemia developed only after the introduction of immunosuppressive medications, which would be consistent with a secondary hypogammaglobulinemia." (PMID 39247195, 2024).
Anxiety (16 papers, 2017 to 2025). Intense feelings of nervousness, tension, or panic often arise in response to interpersonal stresses. "In conclusion, IL-19 plays an essential role in comorbidities related to IBD and anxiety, which can not only control colonic inflammation through the activation of STAT3 but also cause anxiety by down-regulating the ERK-CREB-BDNF pathway." (PMID 36936941, 2023). "S. aureus USA300 infection also upregulated the GLS1 and STAT3‐signaling pathway, implicated with anxiety‐like behaviors." (PMID 35977050, 2022). "The results indicated that the upregulation of GLS1 as well as the NF‐κB/STAT3 signaling pathway in the mPFC drive mount neuroinflammation, which is involved in the development of anxiety‐like behaviors caused by USA300 infection." (PMID 35977050, 2022). "XYS can downregulate the levels of JAK2, phosphorylated -JAK2 and STAT3 in the hippocampus of rats with anxiety behaviors." (PMID 37046230, 2023). "Importantly, glutamate derived from glutaminolysis seems to play an essential role in STAT3 activation, which has been increasingly considered to play a critical role in anxiety." (PMID 35977050, 2022). "The cytokine tumour necrosis factor-α (TNF-α) and its closely associated janus kinase 2 (JAK2)-signal transducer and activator of transcription (STAT3) signalling pathway regulate the neuro-inflammatory response in the brain, thus participating in the development of anxiety." (PMID 28336920, 2017). "Therefore, our research hinted that EGCG might suppress the level of IL‐6 by downregulating STAT3 pathway as well as inhibit apoptosis of hippocampal neuron by decreasing the level of IL‐6, thereby alleviating the anxiety‐like behavior after MI." (PMID 32304289, 2020). "In conclusion, our study demonstrates that minocycline alleviates S. aureus infection-induced neuroinflammation and anxiety-like behaviors by suppressing the TLR2 and STAT3 signaling pathways in microglia." (PMID 40002461, 2025). "Anxiety-like behaviour in the LDB and the EPM was similar between groups (LDB: t47 = 1.324; p = 0.192; n = 24–25/group; EPM: t47 = 1.324; p = 0.192; n = 24–25/group), suggesting that STAT3 knockout in serotonergic neurons does not influence anxiety-like behaviour in a situation of free choice." (PMID 33046834, 2021). "To investigate whether the rescue of depressive‐ and anxiety‐like behaviors in CUMS rats as achieved with overexpression of 204–5p involves downregulation of the JAK2‐STAT3 signaling pathway, we examined the protein levels of JAK2 and p‐STAT3 in CUMS rats with an overexpression of miR‐204‐5p." (PMID 39792918, 2025).
astrocytoma (16 papers, 2012 to 2025). "To determine whether STAT3 was associated with the clinical outcome of astrocytoma, we examined STAT3 expression and activation in 68 human astrocytoma samples." (PMID 24386409, 2013). "Furthermore, the association of STAT3/pSTAT3Tyr705 with prognosis in astrocytoma patients was determined." (PMID 24386409, 2013). "Astrocytoma cells’ viability significantly decreased compared with normal astrocytes after being treated with STAT3 siRNA." (PMID 38067351, 2023). "STAT3 siRNA-treated A172 and T98G astrocytoma cells had different morphology, e.g., cells were smaller and more rounded than wild correspondent types." (PMID 38067351, 2023). "A higher percentage of apoptotic nuclei, a higher level of caspase-3 protein, and a higher percentage of apoptotic cells among STAT3-silenced astrocytoma cells suggested that STAT3 plays an important role in inhibiting apoptosis." (PMID 38067351, 2023). "Analysis of STAT3 and STAT3 tyrosine 705 phosphorylation in human astrocytes and astrocytoma cell lines showed that STAT3 was overexpressed and overactivated in cancer cells." (PMID 38067351, 2023). "As an underlying mechanism, it was found that in high‐grade astrocytoma, mainly GBM, interleukin 11 (IL‐11) secreted by microglia activates STAT3‐MYC signaling." (PMID 36776000, 2023). "Based on the vital role of STAT3 in the malignancy of tumor cells, inhibition of STAT3 in astrocytoma cells can diminish the mortality resulted from this disorder." (PMID 31569687, 2019). "STAT3 activation is found to be higher in GBM than in low-grade astrocytoma, and it is co-expressed with EGFR in GBM." (PMID 31215502, 2019). "Histopathology of the subcutaneous tumors produced by GBMX16, and STAT3-KD and WT-STAT3 rescued GICs showed that they were both high-grade astrocytomas." (PMID 29774125, 2018). "In the present study, we first evaluated the biological significance of STAT3 in astrocytoma cells adhesion and invasion." (PMID 24386409, 2013). "In our previously study, we had ever detected the expressions of JAK2 and pJAK2Tyr1007/Tyr1008, STAT3’s upstream, in the normal cortex and human astrocytoma tissues using immunohistochemistry." (PMID 24386409, 2013). "Recent studies have revealed that knockdown of signal transducers and activators of transcription 3 (STAT3) expression by RNAi induces apoptosis in astrocytoma cell." (PMID 24386409, 2013). "Correlation between STAT3, pSTAT3Tyr705 and clinicopathological characteristics in astrocytoma patients." (PMID 24386409, 2013). "Recent studies have revealed that knockdown of STAT3 expression by RNAi induces apoptosis in astrocytoma cells." (PMID 24386409, 2013). "In the present work, we assess the biological significance of STAT3 in astrocytoma invasion, and evaluate the relationship with astrocytoma prognosis." (PMID 24386409, 2013). "Similarly, in an astrocytoma cell line, inhibition of STAT3 expression with STAT3-specific small interfering RNA (siRNA) increased caspase-dependent apoptosis and decreased expression of STAT3 target genes survivin and Bcl-XL." (PMID 38339245, 2024). "STAT3 mRNA expression was higher in astrocytoma (A) than in oligodendroglioma." (PMID 32483429, 2020). "STAT3 knockdown promotes the sensitivity of astrocytoma cells into apoptosis." (PMID 31569687, 2019). "In conclusion, STAT3 may affect astrocytoma invasion, expression of pSTAT3Tyr705 is a significant prognostic factor in tumor recurrence and overall survival in astrocytoma patients." (PMID 24386409, 2013). "The overall aim of this study was to determine the precise roles of STAT3 in human astrocytoma progression, and to test the hypothesis that STAT3 signaling may be a novel predictor of astrocytoma prognosis and a potential therapeutic target." (PMID 24386409, 2013). "In addition, STAT3 expression and activation were quantified using immunohistochemistry in human astrocytoma samples to determine the relationship with prognosis and clinical outcome." (PMID 24386409, 2013).
astrocytoma (continued). "In summary, our data demonstrate that STAT3 may affect astrocytoma invasion, expression of pSTAT3Tyr705 is a significant prognostic factor in tumor recurrence and OS in astrocytoma patients." (PMID 24386409, 2013). "Furthermore, levels of STAT3’s downstream target, Survivin correlate with astrocytoma grade and may be predictive of poor patient survival." (PMID 28160777, 2017). "Also, studies have proposed that STAT3 signaling may be involved in cell viability and apoptosis regulation in astrocytoma carcinogenesis." (PMID 24386409, 2013). "Thus, STAT3 may provide a potential target for molecular therapy in human astrocytoma, and pSTAT3Tyr705could be an important biomarker for astrocytoma prognosis." (PMID 24386409, 2013). "Therefore, STAT3 may provide a potential target for molecular therapy in human astrocytoma, and pSTAT3Tyr705could be an important biomarker for astrocytoma prognosis." (PMID 24386409, 2013). "Thus, for the first time, we provide mechanistic evidence that STAT3 might affect astrocytoma invasion by multiple mechanisms including contribution to epithelial-mesenchymal transition progression, enzymes-based degradation of the ECM, angiogenesis, adhesion and invasion." (PMID 24386409, 2013). "Nevertheless, the distinct roles of STAT3 in astrocytoma’s invasion and recurrence have not been elucidated." (PMID 24386409, 2013). "Nevertheless, thus far, the distinct roles of STAT3 in astrocytoma’s invasion and recurrence have not been elucidated, nor have the downstream targets been evaluated." (PMID 24386409, 2013). "Third, treatment with STAT3 siRNA reduces VEGF secretion by GBM cells, suggesting that STAT3 could regulate astrocytoma invasive capability by affecting angiogenesis." (PMID 24386409, 2013). "However, the precise roles of STAT3 signaling in human astrocytoma invasion and recurrence have not been fully characterized." (PMID 24386409, 2013).
candidiasis (16 papers, 2016 to 2026). Infection with the organism Candida. "Candidiasis often occurs in individuals with an inherited (gene mutations RORγ, RORγt, STAT3, TRAF3IP2, IL-17F, IL-17RA, IL-17RC) or acquired (drug-induced) dysregulation of IL-17." (PMID 40863217, 2025). "STAT1 gain of function mutations affecting the STAT3/interleukin 17 (IL‐17) pathway causes selective susceptibility to fungal (candida) infections." (PMID 40625894, 2024). "Mutations affecting the STAT3/interleukin 17 (IL‐17) pathway cause selective susceptibility to fungal (candida) infections." (PMID 40625894, 2024). "Congenital immunodeficiencies with candidiasis, T lymphocyte dysfunction, and IL-17 deficiency have been described in the context of pathogenic variants in genes such as STAT3, CARD9, DOCK8, ACT1, IL-17RC, IL-17RA, and IL-17F—where fluconazole is the first-line treatment." (PMID 40686918, 2025). "Considering that candidiasis is caused by the production and release of proinflammatory cytokines, the STAT3 pathway becomes an essential regulator of inflammation and cell death in the oral epithelial when exposed to an inflammatory condition like immunosuppression and oral candidiasis." (PMID 36764307, 2023). "Interestingly, patients with GOF mutations in STAT1 also display defects in the generation of Th17 cells and susceptibility to candida infections demonstrating that balanced STAT1/STAT3 signaling is required for generation of these cells." (PMID 29472924, 2018). "STAT3 is a transcription factor that regulates the differentiation and function of Th17 cells, which are essential for the defense against Candida infections on mucosal surfaces." (PMID 38003833, 2023). "Recently, defects in CARD9 and STAT3 have been found to cause IFI with gastrointestinal manifestations and mutation in STAT3 results in reduced Th17 cells causing candidiasis." (PMID 34490039, 2021). "Candida infections (ranging from mucosal to bloodstream, including deep-seated infections) are influenced by genetic variants in the human genomes like polymorphism in signal transducer and activator of transcription protein-coding genes STAT1 and STAT3." (PMID 34490039, 2021). "Together, this not only demonstrates an essential requirement for STAT3 signaling in the generation of human Th17 cells but also provides an explanation for the CMC observed in AD-HIES patients as IL-17-mediated immunity is crucial for control of candida infections." (PMID 29472924, 2018).